AQP5 (aquaporin 5)
Diseases named in the same sentence as AQP5 in open-access papers (continued):
Sharing a sentence is not in itself a finding about the gene and the disease.
cancer (67 papers, 2008 to 2026). A tumor composed of atypical neoplastic, often pleomorphic cells that invade other tissues. "Aquaporins, including AQP5, have been implicated in various aspects of cancer biology, such as cell migration, proliferation, and angiogenesis." (PMID 37658903, 2023). "We found an increased abundance of the transcription factors AHDC1 and ERF, as well as proteins associated with cancer stemness (AQP5 and ASB6), which were higher expressed in SBT-MP when compared to SBT." (PMID 38014221, 2023). "Previous studies reported that AQP5 was associated with the formation and progression of various cancers." (PMID 37925175, 2023). "Many studies have proven that AQP5 is closely associated with the migration and proliferation of cancer cells, and it can become a prognostic marker and potential drug target." (PMID 33343628, 2020). "AQP5 over-expression is associated with poor prognosis of patients, and the cancers with high AQP5 exhibit EMT and activation of signaling cascades such as EGFR/ERK/p38 MAPK pathway." (PMID 30555637, 2018). "AQP5, aquaporin 5, is a water channel protein involved in pulmonary secretions, and elevated expression of AQP5 is associated with poor survival outcome in many types of cancer." (PMID 29285217, 2017). "In addition to their transport activity, the overexpression of AQP1, AQP3 and AQP5 in cancer has been associated with signal transduction pathways and cytoskeleton reorganization, resembling mechanisms typically mediated by receptors." (PMID 39941100, 2025). "In NSCLC tissues, AQP5 has multiple associations with the progression of cancer." (PMID 38336645, 2024). "Co-culture of metaplastic gastroids with the characteristics of spasmolytic polypeptide-expressing metaplasia with either metaplasia-derived or cancer-derived fibroblasts caused loss of metaplastic markers CD44v9 and AQP5 expression and gain of dysplasia markers TROP2 and CEACAM5 expression." (PMID 37196797, 2023). "Increased AQP5 levels have been associated with invasion and metastasis in various tumor types, such as breast, ovarian, prostate, colon, liver, and lung cancers." (PMID 35163313, 2022). "AQP5 has been implicated in carcinogenesis and its tissue expression might be associated with cancer aggressiveness." (PMID 27983600, 2016). "Considering the number of studies reporting the consistent implication of AQP1, AQP3 and AQP5 in the development of multiple cancer types and their strong association with signaling pathways, this review is focused on the critical roles of these AQPs as transceptors involved in cancer progression." (PMID 39941100, 2025). "Changes in aquaporin (AQP) expression, associated with CSCs and cancer cell migration, was assessed by immunodetection and RT‐qPCR, indicating a decrease in AQP3, AQP5 and AQP6 gene and protein expression upon DM treatment." (PMID 41318947, 2026). "This review explores the pivotal roles of AQP1, AQP3 and AQP5 as transceptors in cancer biology, underscoring their importance as pharmacological targets." (PMID 39941100, 2025). "We assessed cell viability, intracellular ROS, changes in AQP3 and AQP5, and key antioxidative and cancer-related pathways (NRF2, PI3K/AKT, FOXOs)." (PMID 40244097, 2025). "In this context, AQP5 mediates water flow and the decrease or increase in AQP5 expression suppresses or enhances, respectively, cancer cell migration." (PMID 39977018, 2025). "The preferential phosphorylation of the cAMP-protein kinase (PKA) consensus site on AQP5 promoted cancer cell proliferation." (PMID 38336645, 2024). "AQP5 was suggested as an enhancer of cancer cell proliferation, migration, and survival by interacting with different pathways." (PMID 39125952, 2024). "Metaplastic gastroids that were cocultured with metaplasia- or cancer-derived fibroblasts showed decreases in the metaplastic markers AQP5 and CD44v9 and increases in the dysplastic markers TROP2 and CEACAM511." (PMID 38825636, 2024).
cancer (continued). "Treatment with EGCG (20–100 μg/mL) also inhibited cancer cell infiltration and metastasis by downregulating aquaporin 5 (AQP5), NF-κB, and p65." (PMID 36765820, 2023). "Overall, our report shows similar trend to other report between AQP5 expression and its impact on aggressiveness of cancer behavior and prognosis, while some of the details of findings show noticeable differences." (PMID 36706090, 2023). "In other cancers, including prostate, non-small cell lung, colon, and cervical cancers, overexpression of AQP5 correlated with metastases to lymph nodes." (PMID 36768212, 2023). "Numerous studies have demonstrated that AQP5 can be an effective therapeutic target in the fight against cancer." (PMID 36766810, 2023). "In hepatitis B- virus (HBV)-induced hepatocarcinoma, miR-1271-5p has been shown to target Aqp5 mRNA, and its overexpression resulted in decreased Aqp5 expression to block the cancer progression by reducing cell viability, migration, and invasion." (PMID 36768212, 2023). "Then, we have focused on the clinicopathologic variables among cancer tissue samples with strong AQP5 expression (3+ expression, 60/591 cases)." (PMID 36706090, 2023). "In similar cancers, miR-325-3p also targeted Aqp5 mRNA, and its overexpression inhibited cell proliferation and induced cell apoptosis." (PMID 36768212, 2023). "AQP5 has been shown to activate the Ras-MAPK signaling pathway in some cancers, and several mechanisms have been proposed to account for this activation." (PMID 36768212, 2023). "Based on the expression pattern from tissue microarray, we have focused on the clinicopathologic variables among cancer tissue samples with strong AQP5 expression (3+ expression, 60/591 cases)." (PMID 36706090, 2023). "Aquaporins (AQs) transport water molecules and are considered to be overexpressed cancer-promoting factors in a variety of cancers, particularly AQP5." (PMID 36077660, 2022). "AQP5 levels are upregulated in patients with early stage colorectal cancer and facilitate gastric tumor development by augmenting cancer cell invasiveness." (PMID 35163313, 2022). "AQP5 expression also significantly correlated with downstream signaling molecules Rac1 and Ras, a Rho-family member GTPase, and other contributors to cancer migration." (PMID 36212456, 2022). "So far, studies of AQP1, AQP3, and AQP5 involvements in many different cancer types are performed on the basis of numerous cell line, in vivo mice model, and expression profiles of these AQPs in resected cancer tissue samples." (PMID 35847914, 2022). "For this, we see enough pathway activation, leading to EMT and cancer stem cell maintenance at least by AQP5." (PMID 35847914, 2022). "On the other hand, since the occurrence of malignant tumors is related to the microenvironment, in recent years, there have been increasing reports of AQP5 in relation to the occurrence of tumors." (PMID 35619903, 2022). "Of note, our group has initially described novel roles of AQP5 in cancers as a driver of proliferation and invasiveness in vitro and its expression in human resected cancer samples." (PMID 35847914, 2022). "So far, four AQPs (AQP1, AQP4, AQP5, and AQP9) have been linked to EMT in several cancer cell models." (PMID 35847914, 2022). "AQP5 silencing results in the reduced proliferation and migration of human epithelial breast, ovarian, and prostate cancer cells, and reduced AQP5 levels impair EMT in colorectal and metastatic liver cancer cells." (PMID 35163313, 2022). "provided confirmatory evidence for the role of AQP5 in the initiation of gastric carcinogenesis and as a crucial player of cancer stem cell activity." (PMID 35847914, 2022). "We used the TIMER database to analyze the relationship between AQP5 expression and immune cell infiltration in various cancers." (PMID 35619903, 2022). "Further research is warranted to untangle the influence of AQP3 and AQP5 expression in the biophysical properties of cancer cells." (PMID 35455986, 2022).
cancer (continued). "AQP5, in particular, underpinned a recurring theme as a biomarker in diverse cancers, including colon, breast and ovarian." (PMID 32679804, 2020). "Subsequently, we compared the relationship between the expression level of AQP5 and prognosis in 33 kinds of cancers from the TCGA database." (PMID 33343628, 2020). "The contrasting phosphorylation status observed in normal tissues and cancer cells, where AQP5 was found preferentially in the phosphorylated form on Ser156 and Thr259, suggests that AQP5 role in tumorigenesis is related also to its phosphorylation." (PMID 30893772, 2019). "Altogether, these results unveil a major role of AQP5 in cancer progression, highlighting its potential as a drug target for cancer therapies." (PMID 31277235, 2019). "Tissues staged at levels III and IV showed higher levels of AQP5 expression than tissues staged at levels I and II, further indicating the clear role of AQP5 in cancer progression." (PMID 30555637, 2018). "AQP5 up-regulation in different cancer tissues together with markers of cancer progression suggests its involvement in cancer signaling pathways and highlights its potential as promising target for cancer therapy." (PMID 29977890, 2018). "A recent update also showed that cancer cells in confined microenvironments utilized directed water permeation mediated by AQP5 to regulate cell volume through the flux of water, leading to net cell displacement and migration." (PMID 26489517, 2015). "A number of studies have shown that upregulation of AQPs promotes cell proliferation and migration Our data hint at a mechanism whereby phosphorylation of Ser 156 in AQP5 increases its membrane localization, thereby enhancing cancer cell proliferation." (PMID 26569106, 2015). "Some data from malignant tumors suggest that AQP5 over-expression is related to the PI3K phosphorylation and activation of Ras signaling pathways." (PMID 26679484, 2015). "In 19/60 (31.7%) patients, AQP5 expression was strong and in 30/60 (50.0%) patients AQP5 expression was moderate in the cancer group." (PMID 25217331, 2014). "The results showed that AQP5 fluorescence signal is substantially increased in the cancer group compared to the paraneoplastic and normal group." (PMID 25217331, 2014). "Consistent with this, previous studies demonstrated that AQP5-overexpressing cancer cells exhibit the increased ability of cell proliferation and migration via several different signaling pathways." (PMID 22145049, 2011). "We believe that this is the first clinical evidence indicating a strong correlation between AQP5 expression and the outcome of cancer patients who underwent surgery, and further suggest that hAQP5 is a potential independent prognostic marker." (PMID 18478076, 2008). "In conclusion, this is the first report, to our knowledge, to show that human AQP5 is expressed in CML cells with a potential role in cancer progression and plays a role not only in proliferation, but also in survival of CML cells." (PMID 18612408, 2008). "Previous expression studies of AQP5 in human tissues, both normal and malignant, have been only in epithelial tissues and carcinomas." (PMID 18612408, 2008). "Finally, given their roles in cancer progression and the oxidative stress response, we investigated the impact of AQP5 overexpression and H2O2 treatment on PI3K/AKT signaling and FOXO transcription factors." (PMID 40244097, 2025). "Further analysis on cancer cell-specific genes revealed that KPmut-Late tumors exhibit elevated expression levels of several genes, including Prkg2, Hmga2, Wincr1, Cdkn2a, Tnnt2, Aqp5, and Sprr1." (PMID 37998349, 2023). "Considering the high expression of Aqp5 in several cancers (such as breast and lung), it was hypothesized that gene promoter methylation status might account for such observation." (PMID 36768212, 2023).
cancer (continued). "Considering several miRNAs can target the Aqp5 gene, they may be useful for the treatment of various cancers, providing the development of suitable delivery methods and miRNA mimetics." (PMID 36768212, 2023). "Also, we have initiated designing anti AQP5 therapeutic antibody and recently developed 4 novel therapeutic small molecules and have been tested various cancer cell lines with in vitro therapeutic efficacy." (PMID 36706090, 2023). "In this study, we focused on the role of AQP3 and AQP5 because most of the studies demonstrated that these AQPs were significantly increased and played prominent roles in the proliferation, migration, and angiogenesis of cancer." (PMID 35741021, 2022). "We used the UCSC Xena database to analyze AQP5 mRNA expression in pan-cancer and normal tissues." (PMID 35619903, 2022). "Furthermore, AQP3-mediated H2O2 transport has been correlated to breast cancer cell migration, and AQP5 facilitating transmembrane H2O2 diffusion is able to modulate cell proliferation of cancer yeast cells in response to oxidative stress." (PMID 36077720, 2022). "In addition, we analyzed the relationship between the expression of AQP5 and the immune response in 33 cancer types." (PMID 33343628, 2020). "Indeed, AQP1 induces angiogenesis, AQP3 stimulates cellular migration, proliferation or invasion, AQP5 expression correlates to cancer proliferation and migration, and AQP5 and AQP9 regulate chemotherapy resistance." (PMID 32630469, 2020). "Last, we found that AQP5 appeared in all three gene signatures, and through pan-cancer analysis, it was also found to play an important role in immunity in lower grade glioma (LGG), which may contribute to the poor prognosis of LGG patients." (PMID 33343628, 2020). "Altogether, our findings demonstrate that AQP5 can play an important role in cancer cell survival." (PMID 31277235, 2019). "Thus, the current findings support a direct role of AQP5 in cancer development by mediating H2O2 membrane permeation, affecting redox signaling, and influencing signaling transduction pathways involved in tumorigenesis." (PMID 27983600, 2016). "In this context, AQP5 modulation by phosphorylation may represent a novel strategy with potential application in cancer treatment." (PMID 27983600, 2016). "Despite its wide distribution pattern and physiological importance, AQP5 short-term regulation was not reported and mechanisms underlying its involvement in cancer are not well defined." (PMID 27983600, 2016). "Additionally, studies on cancer cell lines suggest that AQP5 plays a significant role in the response to chemotherapy and may promote therapy resistance, highlighting AQP5 as a potential therapeutic target." (PMID 40244097, 2025). "Moreover, the prolonged oxidative stress caused changes in AQP3 and AQP5 expression only in the cancer cell lines, in contrast to their non-malignant counterparts." (PMID 38929065, 2024). "Furthermore, SPEM gastroids under the influence of conditioned media from metaplastic- or cancer-derived fibroblasts recapitulated dysplastic transition with an increase in the dysplasia marker CEACAM5 and a concomitant loss of the metaplasia marker AQP5." (PMID 37196797, 2023). "Therefore, we further analyzed AQP5 to determine whether it has a certain effect on prognosis in other cancer types." (PMID 33343628, 2020). "Selective targeting of AQP5 may open new perspectives for anti-cancer drug development." (PMID 31277235, 2019). "The mechanism of AQP5-facilitated cancer cell invasion and metastasis might be due to its direct or indirect interaction with the epidermal growth factor receptor/extracellular signal-regulated kinase (ERK1/2) pathway, known to be important in cancer metastasis and aggressiveness." (PMID 29922644, 2018). "In addition to trafficking, AQP5 channel activity may be crucial for cancer cell migration and proliferation." (PMID 27983600, 2016).
cancer (continued). "Interestingly, a recent study showed that AQP5 membrane abundance is regulated by phosphorylation, and in fact, the contrasting phosphorylation status between cancer and normal tissues suggests that AQP5 role in tumorigenesis is related with its phosphorylation." (PMID 27983600, 2016). "Presence of AQP5 in cells lining the cysts may suggest a potential role of AQP5 in formation of cystic fluid and secretions possibly required for the survival and growth of cancer cells." (PMID 25344048, 2014). "For NSCLC, AQP5 may be the most interesting candidate for novel anti-cancer therapies." (PMID 21548930, 2011). "In this model, AQP5 showed a highly efficient peroxiporin activity compared to AQP3, revealing the major role of AQP5 in the dynamic fine-tuning of the endogenous concentration of H2O2 and possibly an influence on cancer initiation and progression." (PMID 39125952, 2024). "The expression of DUSP1, AQP5, and BLNK in malignant tumors of the oral region was significantly lower than in normal tissues, according to the TCGA database." (PMID 37925175, 2023). "The results revealed five cancer-promoting genes (AXL, SCG5, VOPP1, DCBLD2, DRAM1), and three tumor suppressor genes (DUSP1, AQP5, BLNK)." (PMID 37925175, 2023). "The eight mRNAs selected for further analysis, AXL, SCG5, VOPP1, DCBLD2 and DRAM1 are cancer-promoting genes, DUSP1, AQP5 and BLNK are cancer suppressor genes." (PMID 37925175, 2023). "We searched and analyzed public cancer databases (GEO, TCGA, HAP, UALCAN, GEPIA, etc.)to conclude that AQP5 expression levels were upregulated in PAAD." (PMID 35619903, 2022). "Similar results have been reported on the reduced proliferation of cancer cell lines by silencing the peroxiporins AQP3, AQP5, and AQP8." (PMID 35741021, 2022). "In a nutshell, the integration of biomechanical and bioimaging tools allow to infer the biological behavior of these cancer cells, suggesting AQP3- and AQP5-targeting as a promising strategy for anticancer therapy." (PMID 35455986, 2022). "Specifically, we described how changes in AQP5 expression and TRPV4 intra-cellular localisation under hyper-osmotic stress depend on the culture condition of different type of cancer cells." (PMID 31551497, 2019). "In other types of cancers, AQP3, AQP4, or AQP5 are increased in expression and influence viability, proliferation and migration." (PMID 31477744, 2019). "Next, we examined the effects of serum depletion on the gene expression of SPC, AQP5, and also hypoxia-inducible factor-1α (HIF-1α) which regulates the phenotypes of cancer cells including their progressive proliferation." (PMID 26167183, 2015). "AQP5 has been shown to activate a wide variety of downstream effectors accounting for cellular functions distinct from water and carbon dioxide permeabilities, including cell migration, invasion, and EMT involved in cancer genesis." (PMID 36768212, 2023). "Moreover, it was shown that up-regulation of AQP5 in certain tumors activates EGFR followed by the activation of the ERK1/2 pathway which leads to proliferation and metastasis potential of cancer cells." (PMID 36114463, 2022). "In addition, AQP5 was the ERG that affected EC patients’ OS, PFS, and DFS, and we further explored its role in other cancer types through pan-cancer analysis." (PMID 33343628, 2020). "Altogether, these results unveiled a major role for AQP5 in dynamic fine-tuning of the intracellular H2O2 concentration, and consequently in activating signaling networks related to cell survival and cancer progression, highlighting AQP5 as a promising drug target for cancer therapies." (PMID 31277235, 2019). "However, the epithelial cells in polypoid structures observed in cultures with conditioned media from metaplasia- or cancer-derived fibroblasts strongly expressed CEACAM5 at the apical side with weak or negative AQP5 expression." (PMID 37196797, 2023).